NECTIN2 (nectin cell adhesion molecule 2)
Diseases named in the same sentence as NECTIN2 in open-access papers (continued):
Sharing a sentence is not in itself a finding about the gene and the disease.
prostate carcinoma (2 papers, 2013 to 2022). A carcinoma that arises from epithelial cells of the prostate gland. "An analysis that compared the mean intensity in each tissue set demonstrated that Nectin-2 was especially over-expressed in breast, ovarian, and prostate cancer tissues." (PMID 23758976, 2013).
acute leukemia (1 paper, 2019). A clonal (malignant) hematopoietic disorder with an acute onset, affecting the bone marrow and the peripheral blood. "Relevant for antileukemia activity, DNAX accessory molecule 1 (DNAM-1) (CD226) can recognize the specific ligands poliovirus receptor (PVR) (CD155) and Nectin-2 (CD112), found to be expressed on various acute leukemias." (PMID 31623224, 2019).
adenoma (1 paper, 2015). A neoplasm arising from the epithelium. "Among the 55 cases with benign pancreatic lesions, the percentages of positive Nectin-2 expression in chronic pancreatitis, adenomas, and intraepithelial neoplasia were 15.0%, 20.0%, and 20.0%, respectively." (PMID 26294807, 2015).
aneurysm (1 paper, 2018). Bulging or ballooning in an area of an artery secondary to arterial wall weakening. "Nectin-2 (PVRL2), a membrane glycoprotein, is involved in cell adhesion, and has been shown to have increased expression in the aneurysm wall tissue." (PMID 30593281, 2018).
breast tumors (1 paper, 2021). "NECTIN2 and NECTIN4 secreted by BCSC interacted with CD96 and TIGIT on immune cells, causing T-cell inhibition and immune escape at primary breast tumors." (PMID 34611125, 2021).
idiopathic thrombocytopenic purpura (1 paper, 2018). "While the anti-tumor effect was promising, the anti-Nectin-2 mAb exhibited unexpected “idiopathic thrombocytopenic purpura (ITP)-like” thrombocytopenia in Cynos." (PMID 29723247, 2018).
intraepithelial neoplasia (1 paper, 2015). A precancerous neoplastic process that affects the squamous, glandular, or transitional cell epithelium without evidence of invasion. "Peritumoral tissues and benign lesions with positive Nectin-2 and DDX3 expression exhibited dysplasia or grade II or III intraepithelial neoplasia." (PMID 26294807, 2015).
kidney infections (1 paper, 2020). "The role of Nectin-2 in kidney infections in vivo need to be further investigated." (PMID 31719643, 2020).
laryngeal squamous cell carcinoma (1 paper, 2025). A squamous cell carcinoma that arises from the larynx. "The main goal of this pilot study was to evaluate the expression patterns of Nectin-2 and Nectin-4 in laryngeal squamous cell carcinoma (LSCC)." (PMID 40699695, 2025).
metastatic cancer (1 paper, 2021). A carcinoma which has spread from the original site of growth to another anatomic site. "By interacting with TIGIT, NECTIN2 was found to be highly expressed in metastatic non-TNBC cells, and by interacting with TIGIT, metastatic cancer cells were found to inhibit T-cell activation and suppress the immune response." (PMID 34611125, 2021).
myocardial ischemia (1 paper, 2018). A disorder of cardiac function caused by insufficient blood flow to the muscle tissue of the heart. "Disease Biomarker Pathway analysis identified Myocardial Ischemia as the third most enriched pathway (FDR-adjusted p = 1.3e−2), featuring 11 SNP loci on our list out of 886 pathway objects, including annexin V, ANRIL, COL4A1, dynein, HXK4, nectin-2, PPAR-gamma, prolidase, Tcf(Lef), UGT, and VEGFR-2." (PMID 29765130, 2018).
ocular infection (1 paper, 2012). "However, nectin-1 is the most relevant receptor for ocular infection, since wild-type HSV-1 fails to use nectin-2." (PMID 23213272, 2012).
pneumonia (1 paper, 2025). An acute, acute and chronic, or chronic inflammation focally or diffusely affecting the lung parenchyma, caused by an infection in one or both of the lungs (by bacteria, viruses, fungi, or mycoplasma.). "Recent research has revealed that individuals carrying a polymorphism in the NECTIN2 gene exhibit a decreased susceptibility to AD when compared to non-carriers, when receiving vaccinations for pneumonia and flu." (PMID 39774485, 2025).
Sepsis (1 paper, 2024). Sepsis is defined as life-threatening organ dysfunction caused by a dysregulated host response to infection. "Our previous studies revealed several novel subtypes of neutrophils, including APANs, nectin-2, and serpin B2 neutrophils, which were found to be upregulated during sepsis." (PMID 38343542, 2024).
squamous cell carcinoma (1 paper, 2025). A carcinoma arising from squamous epithelial cells. "We observed higher expression of immune checkpoint ligands (PVR, NECTIN2, CD274, CD80, and CD86) in the tumor cells at the invasive front of the squamous cell carcinomas." (PMID 41309580, 2025).
Thrombocytopenia (1 paper, 2018). A reduction in the number of circulating thrombocytes. "Unexpectedly, upon administration, Y-443 induced strong thrombocytopenia through Nectin-2 expressed on Cyno platelets, presumably followed by phagocytosis in the mononuclear phagocytic system." (PMID 29723247, 2018). "In this paper, we report that the anti-Nectin-2 antibody Y-443 induces strong thrombocytopenia in Cynos." (PMID 29723247, 2018).
tumor (285 papers, 2009 to 2026). "High expressions of Nectin-2 and Nectin-4 have been linked to tumor invasion, angiogenesis, and immune evasion in various epithelial cancers, indicating their potential as markers for tumor aggressiveness and early detection of premalignant lesions." (PMID 40699695, 2025). "NECTIN2 has been implicated in tumor progression and metastasis by promotion of an immunosuppressive environment via T and NK cell dysfunction." (PMID 40371640, 2025). "ST6GalNAc-I–deficient tumor cells cocultured with T cells were more susceptible to T cell–mediated tumor cell killing, indicating a key role for NECTIN2 in T cell dysfunction." (PMID 40371640, 2025). "The function of NECTIN2 has been implicated in T cell dysfunction that leads to an immunosuppression environment during tumor development." (PMID 40371640, 2025). "We found that TIGIT is mainly expressed on T cells, while the TIGIT ligands, primarily NECTIN2, are expressed on tumor-associated macrophages (TAMs), tumor cells, and endothelial cells, in line with findings from other RCC single-cell RNA studies." (PMID 39105820, 2024). "A significant association was observed between the expression of nectin-2 and tumor location; upon analyzing the adjusted standardized residuals, it was found that the expression of nectin-2 was associated with tumors located in the right half of the colon." (PMID 37958883, 2023). "Our results revealed that diffuse nectin-3 expression was associated with a good prognosis, a higher score for nectin-2 was related to a poorer histological grade and a higher score for nectin-4 was related to a larger tumor size." (PMID 25690753, 2015). "Additionally, tumor-associated neutrophils (TANs), which are also involved in tumor progression, have been linked to the upregulation of NECTIN2." (PMID 41010517, 2025). "Nectin2 may play a role in tumor growth and metastasis, and high levels of expression have been associated with aggressive malignancy, advanced tumor stage, fast progression and poor prognosis." (PMID 36916296, 2023). "The high expression of PVR and Nectin-2 in tumor cells could make them strongly susceptible to DNAM-1 chimeric receptor-engineered NK cell-mediated recognition and killing." (PMID 37359555, 2023). "Nectin-2 and Nectin-4 are often overexpressed in tumours, and are associated with a poor prognosis." (PMID 24386110, 2013). "We hypothesized that this analysis would enhance the knowledge about Nectin-2 and Nectin-4 regarding their potential function as novel biomarkers associated with tumor aggressiveness and metastatic potential in LSCC, contributing to risk stratification and therapeutic decision-making." (PMID 40699695, 2025). "However, even though PVR and Nectin2 overexpression represents a danger signal that renders tumor cells susceptible to cytotoxic cell-mediated lysis, several mechanisms—including the increased expression of inhibitory receptors for these ligands—hamper DNAM-1 activation in advanced tumor stages." (PMID 37760586, 2023). "By analyzing the spatial transcriptome data of two representative tissue pathology samples, we found that NECTIN2 was mainly expressed in tumor tissues, which was consistent with the sequencing results of bulk RNA-seq." (PMID 40855305, 2025). "MUC5AC interacts with NECTIN2 to influence T-cell function and tumor angiogenesis, thereby promoting tumor immune evasion." (PMID 40655139, 2025). "They detected a significant correlation between nectin-2 expression and tumor size, an increased TNM stage, and lymph node metastasis in patients with adenocarcinoma." (PMID 40244005, 2025). "The correlation between inhibition of tumor cell growth and the expression of NECTIN2, ITGB6, and NECTIN1 genes warrants their further investigation as potential biomarkers for oHSV1-FLT3L therapy." (PMID 40955425, 2025).
tumor (continued). "The findings revealed heterogenous expression of both Nectin-2 and Nectin-4 in tumor cells and surrounding stroma, with Nectin-4 expression being significantly higher than Nectin-2 expression." (PMID 40699695, 2025). "On the other hand, the interaction between TIGIT and CD226 attenuates immune operations, while nectin-2 and nectin-4 are identified as promising targets in cancer treatment due to their effects on the behavior of tumor cells." (PMID 40777027, 2025). "The main objective was to evaluate the expression patterns of Nectin-2 and Nectin-4 within the tumor parenchyma and the surrounding stroma." (PMID 40699695, 2025). "Nectin cell adhesion molecule 2 (NECTIN2) is an immunoglobulin-like glycoprotein that plays a role in trans-interactions and modulation of cell-cell contact during tumor progression." (PMID 40371640, 2025). "TIGIT also binds, albeit with less affinity, to CD112, also known as Nectin-2, which is expressed on DCs, monocytes, and numerous tumor cell subtypes." (PMID 40075753, 2025). "TIGIT interacts with its ligands, CD155 (PVR) and CD112 (Nectin-2), which are often overexpressed on tumor cells and antigen-presenting cells (APCs) within the TME." (PMID 40567374, 2025). "Enhanced staining at the invasive tumor margins was observed for both Nectin-2 and Nectin-4, with a more pronounced pattern for Nectin-4, suggesting involvement of this molecule in tumor invasiveness and progression." (PMID 40699695, 2025). "This analysis demonstrated that NECTIN2 was primarily localized around epithelial cells within tumor regions, where it encircled CD8 T cells." (PMID 40855305, 2025). "We observed a high variability in susceptibility to oHSV1-FLT3L infection between the distinct cancer cell lines and found that there was a correlation between the inhibition of tumor cell growth and the expression of NECTIN2, ITGB6, and NECTIN1 genes." (PMID 40955425, 2025). "The primary ligands for DNAM‐1 include the poliovirus receptor (PVR) and Nectin‐2 (CD112), both of which are upregulated on the surface of various tumor cells and in response to cellular stress." (PMID 40959206, 2025). "The UniProt and GlyGen datasets indicate that NECTIN2 has multiple O-glycosylation sites, and it has been shown to be involved in tumor development." (PMID 40371640, 2025). "To investigate NECTIN2 sialylation in tumor cells, we performed an SNA lectin pull-down assay in A549 cells." (PMID 40371640, 2025). "In contrast, Nectin-2 showed weaker expression in both tumor cells and the stroma, with the exception of stronger staining observed in follicular dendritic cells within secondary lymphoid follicles." (PMID 40699695, 2025). "These receptors bind to CD155 (Nexl-5 or PVR) and CD112 (Nectin-2), two ligands ubiquitously expressed at low levels and often found elevated on tumor cells." (PMID 40299429, 2025). "Our findings demonstrate a significantly higher expression of Nectin-4 in tumor cells compared to Nectin-2." (PMID 40699695, 2025). "Nectin-4 demonstrated strong expression in tumor cells and glandular epithelium, whereas Nectin-2 exhibited overall weaker expression, primarily localized to the surrounding stromal tissue and follicular dendritic cells within secondary lymphoid follicles." (PMID 40699695, 2025). "In pancreatic adenocarcinoma, tumor-associated neutrophils (TANs) upregulate Nectin-2, which contributes to tumor progression, promoting CD8+ T-cell exhaustion and facilitating an immunosuppressive tumor microenvironment." (PMID 40699695, 2025). "The results showed that TIGIT and NECTIN2 co-localized spatial in both types of tissues, reflecting that the tumor cells and immune cells communicated frequently through this receptor-ligand axis to create immune-suppressive environment." (PMID 39474422, 2024). "NECTIN2—TIGIT interaction has been reported in other solid tumors, underlining its universality in tumor microenvironments." (PMID 38181797, 2024).
tumor (continued). "Mechanistically, these receptors with opposite effects compete to bind the same ligands, PVR and Nectin-2, which are highly expressed on tumor cells." (PMID 39126041, 2024). "Nectin Cell Adhesion Molecule 2 (NECTIN2, PVRL2/CD112), a member of the Nectin-like molecule family, affects the function of cytotoxic T lymphocytes and inhibits anti-tumor immunity." (PMID 39334513, 2024). "This suggested that the tumor cells expressed NECTIN2 to exert co-inhibitory signals and progressively inhibited an increasing number of immune cell types during tumor progression." (PMID 39474422, 2024). "Coincidentally, they are both ligands for TIGIT, and the expression of PVR and NECTIN2 is strongly correlated with epithelial and endothelial cells, and are more expressed in tumor tissues than in normal tissues." (PMID 39120585, 2024). "Subsequently, our flow cytometry results revealed that PVR, NECTIN2 epithelial cells, endothelial cells, fibroblasts, cDCs, and pDCs concentrated in tumor tissue, as expected." (PMID 39120585, 2024). "Running the ESTIMATE tool on bulk RNA-seq data from the TCGA-LUAD cohort, we calculated the level of tumor immune infiltration and found that high expression of NECTIN2 and PVR genes inhibited immune cell infiltration levels." (PMID 39474422, 2024). "Overall, our findings propose PVR and NECTIN2 as promising biomarkers for prognostic assessment and evaluation of immune infiltration across various tumor types, particularly in LGG and ACC." (PMID 39120585, 2024). "Tumor-associated neutrophils are polarized by TME-triggered ER stress and promote PDAC progression by upregulating CCL5 and Nectin2 expression." (PMID 39261943, 2024). "The rationale for this ICB combination was further substantiated by upregulation of nectin-2 and PD-L1 by tumor cells during co-culture." (PMID 38181797, 2024). "DNAM1 can bind to CD155 and Nectin-2 (CD112), two members of the nectin family present on most tumor cells." (PMID 39415291, 2024). "In SM1, CD226 was expressed in NK cells, and the corresponding ligand in tumor cells was only NECTIN2." (PMID 38528036, 2024). "In the lepidic pattern, the NECTIN2-TIGIT interactions involved tumor cells and NK and Tregs cells, and the interactions extended to encompass tumor cells and CD4+ T/CD8+ T cells with the histologic pattern progression." (PMID 39474422, 2024). "NECTIN2 was exclusively expressed in TAN-0, suggesting that Nectin2+ neutrophils are a subpopulation of tumor-promoting TANs." (PMID 39261943, 2024). "The gene expression profiles on the TCGA-LUAD cohort corroborated that NECTIN2 was highly expressed in tumor tissues." (PMID 39474422, 2024). "TIGIT binds to several ligands, including CD155 (poliovirus receptor) and CD112 (nectin-2), which are both expressed on antigen-presenting cells and tumor cells." (PMID 38254772, 2024). "Nectin2 levels were correlated with tumor stage, with higher levels found in stage IV patients than in patients between stages I and III." (PMID 36916296, 2023). "TIGIT is a co-inhibitory receptor that interacts with its ligands, CD155 (poliovirus receptor) and CD112 (nectin-2), which are expressed on APCs and some tumor cells." (PMID 37345057, 2023). "Nectin2 belongs to the immunoglobulin superfamily and mediates many tumor-related processes, including cell proliferation, migration and invasion." (PMID 36916296, 2023). "In murine models with solid tumors, PVRIG interaction with its ligand NECTIN-2 on tumor or dendritic cells surface suppresses cytotoxic signals, cytokines production, and triggers exhaustion." (PMID 36672396, 2023). "Nectin2 was shown to be highly expressed in the serum of NB patients and correlated with advanced tumor staging." (PMID 36916296, 2023). "Further analysis with clinical data and the cell line study revealed that elevated expression of nectin-2 indicated a more aggressive tumor, since it correlated with tumor size, advanced tumor stage and poor differentiation." (PMID 37568798, 2023).